IL1B (interleukin 1 beta)
Diseases named in the same sentence as IL1B in open-access papers (continued):
Sharing a sentence is not in itself a finding about the gene and the disease.
periodontitis (continued). "Human gingival fibroblasts have been identified as important players in the host response to P. gingivalis, participating in interactions with the bacteria and producing inflammatory cytokines such as IL-1β and IL-6, which have been linked to the pathogenesis of periodontitis." (PMID 39699191, 2025). "Also, other agents with anti-inflammatory properties against IL-1β, including plant-derived substances such as resveratrol and curcumin, well-known polyphenols, have been shown to reduce IL-1β and bone loss in animal models of experimental periodontitis." (PMID 40149874, 2025). "However, some authors have found a statistically significant association between IL1B rs1143634 and periodontitis severity." (PMID 38248068, 2024). "However, increased levels of salivary IL-17A, IL-18 and IL-1B levels were associated with periodontitis." (PMID 38756445, 2024). "TNF-α and IL-1β levels were shown to have an association with periodontitis." (PMID 39410587, 2024). "IL-1β is a most studied member of the IL-1 family and a pro-inflammatory mediator in acute and chronic inflammation, expressed under various disease conditions, such as ischemia, periodontitis, and bone loss." (PMID 38543157, 2024). "Similarly, an elevated level of IL-1β was also detected to be significantly associated (β coefficient = 0.079; p = 0.004) with the incidence of unstable from stable periodontitis." (PMID 39445112, 2024). "Indeed, in young adults, subjects with periodontitis were associated with a higher ratio of interleukin-1 beta and interleukin-10 levels compared to clinically healthy periodontium subjects." (PMID 39857870, 2024). "Periodontitis is an inflammatory disease, often associated with the presence of P. gingivalis in subgingival biofilms, which destroys tissues by releasing pro-inflammatory cytokines such as IL-1β and TNF-α." (PMID 38921772, 2024). "Therefore, this study aimed to determine the diagnostic accuracy of salivary levels of tissue destruction-associated biomarkers (IL-1β and IL-10) for differentiating periodontal health from periodontitis and stable from unstable periodontitis." (PMID 39445112, 2024). "Despite the limitations of this study, salivary IL-1β and IL-10 potentially possess a high diagnostic power for discriminating periodontal health from periodontitis as well as for distinguishing stable from unstable periodontitis." (PMID 39445112, 2024). "OSA may increase the risk of developing periodontitis due to increase of IL-1β and IL-6 in saliva and IL-6, IL-17A and IL-33 in GCF that share the activation of the osteoclastogenesis." (PMID 36967976, 2023). "This peptide at a concentration of 320 μg/mL induces cell death in P. gingivalis Furthermore, in P. gingivalis-induced periodontitis in a rat model, a decrease of IL-1β and TNF-α production and inhibition of bone loss was observed after incubating P. gingivalis with this peptide." (PMID 36897441, 2023). "However, we also noticed that IL-1β was predominantly evident in the patients with grade C periodontitis (p = 0.768), indicating a good association with bone loss." (PMID 36769650, 2023). "The secondary objective was to determine whether correlations existed between miR-155 and IL-1β levels and the extent of patient periodontitis, either alone or in association with CHD." (PMID 37974134, 2023). "Genetic aspects, in particular, the increase in the allelic frequency of single-nucleotide polymorphisms (SNPs) for IL-1 beta (IL-1b) (+3954), SNP IL alpha −889 (IL-1a), and a positive genotype of IL gene increased risk of developing periodontitis within the European Caucasian." (PMID 37998274, 2023).
periodontitis (continued). "Finally, we found that mice with Synoviolin deficiency in myeloid cells had more severe periodontitis and enhanced secretion of IL‐1β and IL‐18 in gingival tissues." (PMID 37506160, 2023). "Thus, in accordance with the findings, the high levels of IL-1β can be linked to the severe form of periodontitis at higher levels." (PMID 35270581, 2022). "A current systematic review and meta-analysis showed that although IL-1B is a noteworthy cytokine biomarker in periodontitis development and progression, different IL-1A polymorphisms may have inverse actions in the pathogenesis of periodontitis." (PMID 36429405, 2022). "Inflammatory factors such as tumor necrosis factor-α (TNF-α), interleukin-1β interleukin (IL)-1β, IL-6, and IL-17 play an important role in the pathology of chronic periodontitis because they cause secondary damage to periodontal tissues thereby exacerbating the destruction of periodontal tissues." (PMID 35942384, 2022). "However, an analysis of frequencies of individuals carrying either allele revealed that the carriage rate of the IL-1B+3953 T allele in periodontitis patients was significantly increased (p = 0.049)." (PMID 36429405, 2022). "It is hypothesized that the increasing salivary IL-1β levels will associate with increasing severity of periodontitis." (PMID 35270581, 2022). "Therefore, our study was designed to determine the prevalence of genetic polymorphisms at the IL-1A−889 and IL-1B+3953 loci in adults with stage III grade B periodontitis and in periodontally healthy individuals." (PMID 36429405, 2022). "The IL-1β rs1143634 polymorphism is associated with susceptibility to myocardial infarction, an aggressive phenotype of breast cancer, and is a predictive factor for a severe course of chronic periodontitis." (PMID 36204643, 2022). "Furthermore, the prevalence of stage III grade B periodontitis was associated with the IL-1B+3953 C/T genotype." (PMID 36429405, 2022). "Hence, the identification of important genetic polymorphisms such as NLRP3 (rs4612666) and IL-1β (+3954) will pave the way for the development of point of care treatment for patients suffering from periodontitis and coronary heart disease." (PMID 34501201, 2021). "IL-1β is a notable cytokine biomarker in periodontitis risk." (PMID 35046930, 2021). "Similarly, IL-1β 3954C>T polymorphism also had a very strong relationship with the periodontitis development with OR (95% CI), 0.66 (0.52–0.80)." (PMID 35046930, 2021). "In addition, the relationship between gene polymorphisms of IL-1α and IL-1β and periodontal disease were significantly different according to the severity of periodontitis." (PMID 34199256, 2021). "Genetic variations of IL-1β + 3954 appear to be associated with increased risk of periodontitis in Koreans (Detection of association between periodontitis and polymorphisms of IL-1beta + 3954 and TNF-alpha −863 in the Korean population after controlling for confounding risk factors)." (PMID 33916672, 2021). "In macrophages, pyroptosis leads to the formation of pores in the plasma membrane which allows secretion of IL-1β and IL-18, cytokines known as damage-associated molecular patterns (DAMPs) and contribute to the progression of periodontitis by increasing cell migration and osteoclastogenesis." (PMID 33467650, 2021). "Consequently, active periodontitis is associated with elevated salivary concentrations of pro-inflammatory mediators, including interleukin-1 beta (IL-1β), interleukin-6 (IL-6), interleukin-8 (IL-8), and tumor necrosis factor alpha (TNF-α)." (PMID 35048079, 2021). "Release of IL-1β into tissues generates a pro-inflammatory microenvironment, inhibits osteoblastogenesis, and promotes osteoclastogenesis, all of which exacerbate the pathological damage caused by periodontitis." (PMID 34970269, 2021). "IL1B gene polymorphisms are a risk factor for periodontitis." (PMID 34177950, 2021).
periodontitis (continued). "The decreased transcript levels of IL-1β induced by the rmlC mutant could be involved in its diminished virulence, as previous works have shown that IL-1β inhibition reduced bone loss in experimental periodontitis." (PMID 33193431, 2020). "Since clinical criteria are inappropriate to measure the degree of susceptibility to progression, IL-1β may be a useful biomarker to improve the early assessment of periodontitis patients at high risk of future breakdown." (PMID 33218047, 2020). "IL-1β is a major player in the periodontal inflammatory process underlying chronic periodontitis." (PMID 30956972, 2019). "IL-1α − 889 and IL-1β + 3954 were strongly associated with the periodontitis." (PMID 30755190, 2019). "IL-1β, which has a wide range of biological activities, is known to have a strong association with the Gingival Index and pocket depth, and levels of IL-1β were significantly lower in healthy gingival tissue than in inflamed tissue in periodontitis patients." (PMID 31027223, 2019). "The aim of this study was to determine whether the IL-1β polymorphism (rs16944) is associated with susceptibility to chronic periodontitis." (PMID 30647799, 2018). "To further investigate the periodontitis pathogenesis in vivo, we performed ligature-induced periodontitis model using IL-37WT and V1 transgenic mice and evaluated the alveolar bone loss and IL-1β level in the gingival tissue." (PMID 30206230, 2018). "The literature suggests that this substance may be an important mediator of attachment loss in human periodontitis, and indicates that IL-1β may be useful for locating sites of periodontal disease activity." (PMID 29075409, 2017). "Hyperparathyroidism increased ABL associated to periodontitis (0.99 ± 0.07 vs. 0.70 ± 0.008 mm, p < 0.001), as well as gingival levels of IL-1β and TNF-α (92.25 ± 6.26 vs. 68.25 ± 5.23 pg/mL for IL-1β, p < 0.01; and 80.73 ± 4.52 vs. 62.85 ± 5.85 pg/mL for TNF-α, p < 0.05)." (PMID 27617985, 2016). "Further studies of IL-1B pathways, inflammasome pathways, and salivary antimicrobial molecules may lead to the identification of a deficiency common to several types of periodontitis." (PMID 28008419, 2016). "Moreover, the combination of the levels of three selected salivary biomarkers, namely MMP-8, IL-1β, and P. gingivalis, was associated with periodontitis better than any of the markers alone." (PMID 26484315, 2015). "Also, one study of some 98 periodontitis patients revealed a positive correlation between levels of salivary IL-1β and the extent of alveolar bone loss." (PMID 24944840, 2014). "IL1α and IL-1β production upregulates prostaglandin E2 and matrix metalloproteinase and, together with these components, promote the loss of connective tissue and bone in periodontitis lesions." (PMID 23691333, 2013). "IL-1β in gingival crevicular fluids of patients with periodontitis reduced significantly after initial periodontal therapy, indicating that IL-1β is associated with periodontitis." (PMID 22761920, 2012). "Similarly to its established role as a diagnostic biomarker in periodontitis, emerging evidence indicates that IL-1β may also support the early detection and prognostic evaluation of OSCC." (PMID 41440367, 2025). "In addition, patients with periodontitis have a higher risk for cardiovascular diseases which could be associated with the elevated levels of IL-1β detected in the cardiovascular disease group." (PMID 39328992, 2024). "In addition, some researchers reported that susceptibility to periodontitis may increase or disease progression which is further accelerated in patients with IL-1β polymorphism." (PMID 39012553, 2024). "Interestingly, the IL-1β/IL-10 ratio showed an improved diagnostic potential (AUC of 1, p < 0.0001) to discriminate between periodontal health from unstable periodontitis (cutoff value >1.35) and stable periodontitis from unstable periodontitis (cutoff value >1.55)." (PMID 39445112, 2024).
periodontitis (continued). "Notably, IL-1β is deemed one of the principal destructive agents in periodontal tissues, making its concentration measurement a valuable diagnostic indicator for active periodontitis." (PMID 39830512, 2024). "IL-1β is one of the factors known to stimulate bone resorption and proteinase secretion, and it may be involved in attachment loss and bone resorption, which are characteristics of periodontitis." (PMID 39074834, 2024). "Thus, IL-1β levels can be used as a diagnostic marker of periodontitis." (PMID 37626627, 2023). "Within the limits of the present study, it can be concluded that the occurrence of stage III grade periodontitis might be associated with IL-1B+3953 T allele and composite IL-1 polymorphism, and a decreased susceptibility appeared to involve IL-1A−889 and IL-1B+3953 C/C homozygosity in adult Poles." (PMID 36429405, 2022). "Similarly, Liu and Li (2022), based on available published data, indicated that the polymorphism of IL-1β may be used as a biomarker in risk of periodontitis assessment." (PMID 35453197, 2022). "We therefore exposed periodontal fibroblasts to IL-1β, which has been shown to be increased at periodontally inflamed sites, and to the periodontopathogen F. nucleatum, which is a gram-negative anaerobic microorganism associated with gingivitis and periodontitis." (PMID 30609928, 2019). "Large inter-individual variations in the cytokine responses were found, leading us to suggest that periodontitis patients secrete more IL-1β and IL-18 when exposed to bacterial H2S compared to healthy individuals, which may indicate a higher susceptibility to developing periodontitis." (PMID 31164964, 2019). "Periodontitis is one of the most common chronic infectious diseases and is caused mainly by gram-negative microaerophilic and anaerobic bacteria that colonize the subgingival area and produce significant amounts of proinflammatory mediators, mainly IL-1β, IL-6, PGE2, and TNF-α." (PMID 28243243, 2017). "Another common pathogenic link affecting periodontitis and RA is the monocytic hypersecretory state, which may induce the secretion of excessive pro-inflammatory cytokine secretion, such as IL-1b, TNF-a and IL-6, which results in the stimulation of degrading enzymes and tissue destruction." (PMID 22035090, 2011). "The expression trends of CFI (upregulated) and COQ2 (downregulated) were first confirmed in TNF-α/IL-1β-stimulated human periodontal ligament cells and further validated in a rat ligature-induced periodontitis model." (PMID 41998822, 2026). "In chronic periodontitis, IL‐1β and TNF‐α were considered to propagate inflammation into deeper connective tissues, promoting loss of attachment, osteoclast activation, and alveolar bone resorption." (PMID 41497811, 2025). "We also observed higher concentrations of the pro-inflammatory marker IL-1β in saliva with increasing age, likely reflecting the greater prevalence of periodontitis and hypertension in older patients and the more frequent presence of localized inflammation." (PMID 40572711, 2025). "In the current study, IL-1β was statistically significantly (p ≤ 0.001) increased in gingivitis versus healthy sites and periodontitis versus gingivitis sites." (PMID 41303313, 2025). "In gingival tissues, the expression levels of NLRP3, Caspase‐1, and IL‐1β were significantly higher in patients with periodontitis than in healthy individuals." (PMID 41298339, 2025). "The JP2 clone, with its heightened leukotoxic activity, induces particularly robust IL-1β responses, correlating with the severe tissue destruction observed in aggressive periodontitis." (PMID 40137780, 2025). "Consequently, attenuating the activity of inflammatory mediators in an IL-1β-rich microenvironment may be an effective therapeutic approach to prevent tissue degradation and alveolar bone loss associated with periodontitis, particularly during orthodontic treatment." (PMID 40863063, 2025).
periodontitis (continued). "In vivo studies have shown that periodontitis patients treated with anti-tumor necrosis factor-α significantly reduced IL-1β and IL-8 levels in gingival sulcus fluid and IL-8 levels in saliva." (PMID 40851867, 2025). "Promoting osteoclastogenesis and tissue destruction, these RANKL, TNF-α, and IL-1β regulators are well-known to induce periodontitis." (PMID 41050338, 2025). "The expression of NLRP3, NLRP2, IL-1β, and IL-18 in gingival tissues from patients with gingivitis, chronic periodontitis, and aggressive periodontitis was upregulated, with positive correlations observed between NLRP3 and its downstream products." (PMID 41440367, 2025). "As IL-1β levels increase in periodontitis and increase over time, it is used as an immunohistochemical marker, and its increase indicates the propagation of periodontitis." (PMID 40692535, 2025). "Tumor necrosis factor alpha (TNF-α), interleukin-1 beta (IL-1β), and interleukin-6 (IL-6) are critical cytokines in the etiology of periodontitis." (PMID 40564062, 2025). "Numerous studies have confirmed that individuals with periodontitis exhibit higher serum levels of inflammatory markers such as IL-1β, TNF-α, IL-17A, IL-6, and lower levels of the anti-inflammatory cytokine IL-10 compared to healthy controls." (PMID 40732209, 2025). "In rats with induced periodontitis, treatment with nootkatone significantly reduced the levels of inflammatory markers, such as IL-1β, IL-6, and TNF-α within the gingival tissue, showcasing its potential to protect against the degradation of alveolar bone." (PMID 40710159, 2025). "According to the literature, IL-1 expression is significantly elevated in diabetic rats with periodontitis, and IL-1β promotes osteoclast formation in patients with rheumatoid arthritis, periodontal disease, and osteoporosis." (PMID 40922724, 2025). "Salivary concentrations and GCF total amount of IL-1β have been indicated to be higher in periodontitis patients than in periodontally healthy individuals." (PMID 39964474, 2025). "Based on the findings of this study, we can conclude that IL-1β, when added throughout the culture period as a mimic of a chronic inflammation such as periodontitis, induces osteoclastogenesis." (PMID 40136507, 2025). "Exosomes obtained from human donors with periodontitis have induced IL-1β and IL-6 production, increased BBB permeability, and crossed the BBB in vitro." (PMID 39860036, 2025). "Analyses of gingival tissues from healthy and periodontitis individuals demonstrated a statistically significant increase in the expressions of IL-1β, TNF-α and ZBP1 in infected tissues." (PMID 40307566, 2025). "This dual modulation supports GLP-1RAs as a potential adjunctive anti-inflammatory therapy in periodontitis by suppressing cytokines such as IL-6, IL-1β, and TNF-α." (PMID 41328144, 2025). "IL-1β functions in periodontitis in three collaborative ways, first by increasing the activity of enzymes that break down tissues." (PMID 40692535, 2025). "Compared with T2DM patients with healthy periodontal conditions, T2DM patients with periodontitis exhibit significantly higher expression of ferroptosis-related genes, such as IL-1β, IL-6, NFE2L2, and ALOX5, in pancreatic tissue." (PMID 40541947, 2025). "Periodontitis induces a local and systemic inflammatory response, with an increase in pro-inflammatory cytokines such as IL-1β, IL-6, and TNF-α." (PMID 40231144, 2025). "Ebersole et al21 and Ramseier et al22 reported higher IL-1β salivary levels in periodontitis than in gingivitis, consistent with our study." (PMID 40265034, 2025). "For salivary IL-1β concentrations, the difference between the control group and the combination of the other groups (gingivitis + periodontitis) was examined." (PMID 39964474, 2025). "Il-1β, Il-6, and Tnf-α levels were increased significantly in the gingiva and cortex in periodontitis mice, which was similar to the results of previous studies." (PMID 40552124, 2025).